LIMA1 (LIM domain and actin binding 1)
Description:
Actin-binding protein involved in actin cytoskeleton regulation and dynamics. Increases the number and size of actin stress fibers and inhibits membrane ruffling. Inhibits actin filament depolymerization. Bundles actin filaments, delays filament nucleation and reduces formation of branched filaments. Acts as a negative regulator of primary cilium formation. Plays a role in cholesterol homeostasis. Influences plasma cholesterol levels through regulation of intestinal cholesterol absorption. May act as a scaffold protein by regulating NPC1L1 transportation, an essential protein for cholesterol absorption, to the plasma membrane by recruiting MYO5B to NPC1L1, and thus facilitates cholesterol uptake (By similarity).
Synonyms: EPLIN; SREBP3; LDLCQ8
Tractability: Antibody: its Gene Ontology location is reachable by antibodies, with high confidence; UniProt places it where antibodies can reach, with medium confidence. PROTAC: UniProt records ubiquitination sites on it; ubiquitination databases record sites on it; its protein half-life has been measured.
Gene: Protein-coding gene on chromosome 12 (50,175,788 to 50,283,524, reverse strand). Ensembl gene ENSG00000050405.
Subcellular location: Cytoplasm; Cell junction, focal adhesion; Cytoplasm, cytoskeleton; Cytoplasm, cytoskeleton, stress fiber; Cell membrane; Cell projection, ruffle; Cell projection, lamellipodium
Subcellular location (Human Protein Atlas): Actin filaments; Plasma membrane; Cytosol; Focal adhesion sites
Gene Ontology:
Molecular function: actin filament binding; actin monomer binding; cadherin binding; microtubule stabilizing activity; protein binding
Biological process: actin filament bundle assembly; negative regulation of actin filament depolymerization; negative regulation of cell migration; negative regulation of cilium assembly; positive regulation of actin filament bundle assembly; regulation of lamellipodium organization; ruffle organization; cell migration; cholesterol homeostasis; intestinal cholesterol absorption
Cellular component: actin cytoskeleton; actin filament; cleavage furrow; cytosol; focal adhesion; lamellipodium; ruffle; stress fiber; brush border membrane; plasma membrane; brush border; cytoplasm; cytoskeleton
Genetic constraint (gnomAD): Loss-of-function variants: 44 observed, 54.49 expected, observed/expected ratio (o/e) 0.81, 90% interval 0.63 to 1.04. The upper end of that interval is the gene's LOEUF score, 1.04, which puts it in group 4 of 6, group 1 being the genes least tolerant of losing a copy. Missense variants: 720 observed, 868.67 expected, observed/expected ratio (o/e) 0.83, 90% interval 0.78 to 0.88. Synonymous variants: 273 observed, 304.38 expected, observed/expected ratio (o/e) 0.9, 90% interval 0.81 to 0.99.
Homologues: Orthologues: chimpanzee LIMA1 (95% identical), pig LIMA1 (82% identical), rabbit LIMA1 (82% identical), dog LIMA1 (81% identical), guinea pig LIMA1 (78% identical), rat Lima1 (74% identical), mouse Lima1 (61% identical), macaque CERS5 (58% identical), tropical clawed frog lima1 (46% identical), zebrafish lima1a (31% identical).
Diseases named in the same sentence as LIMA1 in open-access papers:
LIMA1 is named in the same sentence as 63 diseases in open-access papers, as found by Europe PMC text mining. Sharing a sentence is not in itself a finding about the gene and the disease. The quoted sentences say what the papers report.
breast carcinoma (13 papers, 2008 to 2026). "LIMA1 is associated with the progression and metastasis of various solid tumors including oral cancer, esophageal cancer, gastric cancer, prostate cancer, breast cancer, ovarian cancer, and head and neck squamous cell carcinoma, as well as osteosarcoma and lymphoma." (PMID 37274282, 2023). "Together, our results demonstrate that LRP5 in osteocytes inhibits effects on breast cancer cells primarily by activating the LIMA1/MYO5B signaling axis." (PMID 41596426, 2026). "LIMA1 has been documented as a metastasis suppressor in breast cancer, a finding corroborated by our multi-omics analyses showing significant LIMA1 downregulation in TNBC versus paracancerous tissues across FUSCC transcriptomic and proteomic datasets." (PMID 41540000, 2026). "In this context, the prognostic predictive effects and therapeutic potential of LIMA1 in breast cancer warrant further exploration." (PMID 41540000, 2026). "In summary, this study revealed that LRP5 overexpression in bone cells significantly inhibited breast cancer cell proliferation, migration, and invasion, and regulated osteoclast differentiation and immune response by activating the LIMA1/MYO5B signaling axis." (PMID 41596426, 2026). "The inhibitory effect of LIMA1 on ovarian cancer cell growth is in line with findings in breast cancer, prostate cancer, esophageal cancer, and endothelial cell lines." (PMID 37274282, 2023). "Their interaction leads to LIMA1 degradation, thus decreasing its expression in breast cancer tissue (p-value <0.05)." (PMID 32938402, 2020). "Here, we show that conditioned medium from LRP5-overexpressing MLO-A5 osteocytes markedly inhibits EO771 breast cancer cell proliferation, migration, and invasion, and alters the expression of key tumor-related proteins—effects that are mediated by upregulation of LIMA1." (PMID 41596426, 2026). "In vivo, systemic administration of LRP5-overexpressing osteocyte-derived conditioned medium reduced mammary tumor burden and mitigated osteolytic bone destruction in tibial metastasis, whereas genetic disruption of LIMA1 in osteocytes or MYO5B in tumor cells abrogated these protective effects." (PMID 41596426, 2026). "It is evident that LIMA1 is a negative regulator of breast cancer cell migration." (PMID 37274282, 2023). "Furthermore, there is a clear clinical correlation between the LIMA1 expression and tumor grade, lymph node status and tumor stage of breast cancers." (PMID 37274282, 2023). "Thus, it is hypothesized that LIMA1 is an important prognostic indicator and could be considered as an important target during targeted breast cancer therapy in the future." (PMID 37274282, 2023). "In mouse models of breast cancer and breast cancer bone metastasis, LRP5-overexpressing osteocyte-derived CM markedly reduced tumor burden and osteolytic lesions, whereas genetic knockdown of either LIMA1 or MYO5B abolished these protective effects." (PMID 41596426, 2026). "A) filtering for Breast Cancer (BRCA) tissue, ceRNA network analysis evidenced an interaction between LIMA1 gene, has-miR-20b and has-miR-17 cluster and ncRNA RP11-1000B6.3 (Ensembl ID: ENSG00000261064)." (PMID 32938402, 2020). "Co-immunoprecipitation and immunofluorescence co-localization analyses revealed a specific interaction and spatial co-localization between exogenous LIMA1 and MYO5B in breast cancer cells, demonstrating that MYO5B is required for LIMA1-mediated inhibition of tumor cell migration and invasion." (PMID 41596426, 2026). "Similarly, LIMA1 depletion was found to promote EMT and induced actin cytoskeleton remodeling in breast cancers and epithelial ovarian cancers significantly enhancing the migration and invasion of epithelial cancer cells both in vivo and in vitro." (PMID 37274282, 2023).
breast carcinoma (continued). "In syngeneic mouse models of mammary tumors and bone metastasis, systemic administration of LRP5-overexpressing osteocyte-derived CM reduced tumor burden and osteolytic bone destruction, whereas genetic knockdown of LIMA1 in osteocytes or MYO5B in tumor cells abrogated these protective effects." (PMID 41596426, 2026).
prostate carcinoma (10 papers, 2015 to 2026). A carcinoma that arises from epithelial cells of the prostate gland. "Previous studies have reported that LIMA1 expression is downregulated in several epithelial cancers, including breast and prostate cancer." (PMID 41596426, 2026). "The use of the ARCaP EMT model was demonstrated by the understanding of LIMA1 biology and the ARCaP model in the discovery of new drugs for the prevention and treatment of prostate cancer metastasis." (PMID 37274282, 2023). "Research on LIMA1 in urologic system tumors is currently focused on prostate cancer." (PMID 37274282, 2023). "Thus, it is evident that these studies confirmed the importance of LIMA1 in prostate cancer and further highlighted the importance of LIMA1 in regulating the growth and aggressiveness of prostate cancer cells." (PMID 37274282, 2023). "LIMA1 is a negative regulator of EMT and invasiveness in prostate cancers, inhibiting E-cadherin, activating β-catenin signaling pathway and enhancing chemoresistance." (PMID 37274282, 2023).
head and neck squamous cell carcinoma (6 papers, 2015 to 2026). A squamous cell carcinoma that arises from any of the following anatomic sites: lip and oral cavity, nasal cavity, paranasal sinuses, pharynx, larynx, and salivary glands. "However, LIMA1 is upregulated in head and neck squamous cell carcinoma, which is triggered by DNA demethylation of its promoter region." (PMID 41540000, 2026). "Notably, another study has identified LIMA1 overexpression in the head and neck squamous cell carcinoma (HNSC)." (PMID 37274282, 2023).
colorectal cancer (5 papers, 2008 to 2023). A primary or metastatic malignant neoplasm that affects the colon or rectum. "Consistently, higher LIMA1 levels correlate with poorer overall survival of colorectal cancer patients." (PMID 37325974, 2023). "Consistently, analysis of several human colorectal cancer gene expression datasets showed that survival rates were significantly reduced among the patients with tumors expressing relatively higher levels of LIMA1 (denoting EPLIN-β) compared to those with lower LIMA1 levels." (PMID 37325974, 2023). "Furthermore, Kaplan–Meier analysis of survivability in a colorectal carcinoma dataset (GSE17536) from PrognoScan indicated that higher levels of LIMA1 (EPLIN-β only) are correlated with a significantly lower survival probability." (PMID 37325974, 2023).
gastric cancer (5 papers, 2021 to 2024). A primary or metastatic malignant neoplasm involving the stomach. "Initially larger gastric cancer cohort to assess the association between LIMA1 expression and clinico-pathological features and prognosis." (PMID 37274282, 2023). "Similarly, high expression levels of LIMA1 were also significantly associated with increased FP time in gastric cancer patients (HR = 0.63, 95% cl 0.52–0.78; p = 8 × 10−6)." (PMID 33917939, 2021). "The current research hot-spots on LIMA1 in digestive system tumors are mainly focused on esophageal cancer and gastric cancer." (PMID 37274282, 2023). "This will provide new targets for biomarkers or therapeutic strategies related to LIMA1 in gastric cancer." (PMID 37274282, 2023). "This resource was used to explore LIMA1 (Affymetrix ID: 217892_s_at) expression and its relation to gastric cancer patient survival rates." (PMID 33917939, 2021). "Significantly longer PPS was also observed in gastric cancer patients who had high LIMA1 expression compared with those with relatively low LIMA1 expression (HR = 0.65, 95% cl 0.52–0.81; p = 0.00011)." (PMID 33917939, 2021). "Gastric cancer patients with high expression of LIMA1 had a significantly longer OS than those with low expression of LIMA1 (HR = 0.67, 95% cl 0.57–0.8; p = 3.9 × 10−6)." (PMID 33917939, 2021). "Therefore, further studies and larger cohorts are necessary in the future the better to understand the role of LIMA1 in gastric cancer, particularly regarding its involvement in chemoresistance and therapeutic response." (PMID 37274282, 2023). "LIMA1 negatively regulates biological function in gastric cancers requiring NAC and may promote longer overall survival." (PMID 37274282, 2023). "It is suggested that LIMA1 may be a potential prognostic indicator for gastric cancer." (PMID 37274282, 2023). "We analysed the relationship between the expression of LIMA1 and the OS, FP and PPS of gastric cancer patients." (PMID 33917939, 2021).
oral cancer (5 papers, 2008 to 2023). "Encoded by the LIMA1 gene, Epithelial Protein Lost In Neoplasm (EPLIN) was initially discovered to be downregulated in oral cancer." (PMID 36499558, 2022). "LIMA1 was initially found to be a downregulated gene in oral cancer." (PMID 37274282, 2023).
atherosclerosis (3 papers, 2019 to 2023). A disease characterized by the build-up of fatty material and calcium deposition in the arterial wall resulting in partial or complete occlusion of the arterial lumen. "Endou, Hdac7, Senp1, Olfr286, Olfr285, Nckap5l, Smarcd1, Lima1, Fam186a, and Espl1 are probable candidate genes for distal Chr15 atherosclerosis QTL (Ath53)." (PMID 36078077, 2022).
cholangiocarcinoma (3 papers, 2020 to 2026). A carcinoma that arises from the intrahepatic biliary tree (intrahepatic cholangiocarcinoma) or from the junction, or adjacent to the junction, of the right and left hepatic ducts (hilar cholangiocarcinoma). "Previous studies have reported that deubiquitinase USP44 participates in the degradation of LIMA1 in cholangiocarcinoma." (PMID 41540000, 2026).
hepatocellular carcinoma (3 papers, 2023 to 2026). A malignant tumor that arises from hepatocytes. "Another study suggests that cancer associated fibroblasts (CAF) deploy miR-20a-5p-loaded exosomes to silence LIMA1 in hepatocellular carcinoma." (PMID 41540000, 2026). "Our study found that the LIMA1 was highly expressed in hepatocellular carcinoma tissues and cell lines." (PMID 37274282, 2023). "Overexpression of LIMA1 enhanced the migration and invasion of hepatocellular carcinoma cells, which conflicted with our previous knowledge of LIMA1." (PMID 37274282, 2023). "However, the role and regulatory mechanisms of LIMA1 in hepatocellular carcinoma are still not well understood, and its biological function and clinical value need to be further explored." (PMID 37274282, 2023). "There are no published articles on the effect of LIMA1 on the malignant phenotype of hepatocellular carcinoma." (PMID 37274282, 2023).
MALT lymphoma (3 papers, 2016 to 2025). An indolent, extranodal type of non-Hodgkin lymphoma composed of small B-lymphocytes (centrocyte-like cells). "In addition to cleaving NIK, the IAP2-MALT1 fusion protein has recently been shown to cleave the tumor suppressor protein LIMA1, and LIMA1 cleavage products are present in MALT lymphoma samples expressing IAP2-MALT1." (PMID 26507244, 2016). "Interestingly, it was also shown that API2-MALT1-mediated protein hydrolysis produced a LIM domain-only containing oncogenic characteristic fragments both in vivo and in vitro, implying that API2-MALT1 converted LIMA1 into an oncogenic LIM domain-only-like protein in MALT lymphoma." (PMID 37274282, 2023).
melanoma (3 papers, 2014 to 2022). A malignant, usually aggressive tumor composed of atypical, neoplastic melanocytes. "We recently reported that DNp73 promotes melanoma metastasis by triggering EMT, cell migration and invasion, which is achieved by direct interference with wild-type p73-dependent stimulation of the tumor suppressor LIMA1/EPLIN." (PMID 25071017, 2014).
ovarian carcinoma (3 papers, 2021 to 2023). A malignant neoplasm originating from the surface ovarian epithelium. "LIMA1 has the potential to be used as a prognostic predictor and this molecule, in patients with epithelial ovarian cancer, acts as a protective factor." (PMID 37274282, 2023).
Hepatic fibrosis (2 papers, 2024 to 2025). The presence of excessive fibrous connective tissue in the liver. "LIMA1 enriched LTH-sEV play an important role in promoting HSC activation in NAFLD-associated liver fibrosis." (PMID 38822260, 2024). "LIMA1 plays a crucial role in inhibiting autophagy and promoting HSCs activation and the progression of liver fibrosis by LTH-sEV." (PMID 38822260, 2024). "To investigate the role of LTH-sEV derived LIMA1 in promoting NAFLD-related liver fibrosis, we injected LTH-sEVshCtr and LTH-sEVshLIMA1 into HFD mice through the tail vein." (PMID 38822260, 2024). "Lipotoxic hepatocyte-derived LIMA1-enriched sEVs play a crucial role in promoting HSCs activation in NAFLD-related liver fibrosis by negatively regulating PINK1 mediated mitophagy." (PMID 38822260, 2024). "The expression levels of LIMA1 in liver tissue and serum sEV of clinical NAFLD patients are still unknown, and further investigation is needed to understand the relationship between LIMA1 and the progression of clinical liver fibrosis." (PMID 38822260, 2024). "Currently, studies on LIMA1 mainly focus on cancer progression and intestinal cholesterol absorption, whereas the role of LIMA1 in HSCs activation and liver fibrosis remain virtually unknown." (PMID 38822260, 2024). "However, the specific contribution of LIMA1 in HSCs activation and the progression of liver fibrosis remains unclear." (PMID 38822260, 2024). "Finally, sEV was injected to investigate whether LIMA1 can accelerate HFD induced liver fibrosis in mice." (PMID 38822260, 2024). "Notably, LIMA1 HKO exhibited systematic amelioration of MASLD‐related phenotypes, as indicated by the changes in hepatic steatosis, inflammatory cell infiltration, and hepatic fibrosis in HFD‐fed and CDAHFD‐fed mice." (PMID 39921472, 2025).
lung carcinoma (2 papers, 2021 to 2025). "This suggests that hsa_piR_019822 may influence LIMA1 expression or function, potentially contributing to lung cancer progression." (PMID 40243460, 2025).
lymphoma (2 papers, 2015 to 2023). A malignant (clonal) proliferation of B- lymphocytes or T- lymphocytes which involves the lymph nodes, bone marrow and/or extranodal sites. "Overall, specific inhibition of the interaction between API2 and LIMA1 may facilitate the development of targeted therapies against API2-MALT1 positive lymphomas." (PMID 37274282, 2023). "This may be explained by cell type specificity of certain protease-substrate interactions as we analyzed B cells, whereas Roquin and Regnase-1 are described in literature as substrates in T cell-specific processes, and LIMA1 and NF-κB-induced kinase (NIK) are lymphoma-enriched substrates." (PMID 26525107, 2015).
metastatic disease (2 papers, 2023 to 2025). "Expanding our exploration of multiple areas of this important molecule, LIMA1, in the future will increase its therapeutic potential and help design new metastatic disease prevention and treatment." (PMID 37274282, 2023).
pancreatic cancer (2 papers, 2024 to 2025). "Notably, indicating that the prognostic role for LIMA1 could be extended at least to some other cancer types, statistically significant reduction of OS was observed also in TCGA cohort of pancreatic cancer treated with curatively intended surgery (P = 0.009, Fig. EV2B)." (PMID 40676267, 2025).
thyroid cancer (2 papers, 2016 to 2022). "Enhanced LIMA1 expression in HNSCs also increases thyroid cancer, bladder cancer, the progression of prion disease, and bacterial penetration into host cells." (PMID 37181789, 2022). "The up-regulation of LIMA1 mRNA under hyper-g indicates a mechanism of the thyroid cancer cells to stabilize the actin cytoskeleton." (PMID 26818711, 2016). "Five pathways had the strongest positive link with LIMA1 expression, according to KEGG pathway analysis: circadian rhythm animal, glycosaminoglycan biosynthesis chondroitin sulfate, thyroid cancer, bladder cancer, and prion disorders." (PMID 37181789, 2022).
fatty liver (1 paper, 2025). "Analysis of lipometabolic gene expression also validated the impact of LIMA1 deficiency on hepatic steatosis." (PMID 39921472, 2025). "Analysis of lipometabolic gene expression also validated the impact of LIMA1‐WT and LIMA1ΔT662 on hepatic steatosis." (PMID 39921472, 2025).